RECK (reversion inducing cysteine rich protein with kazal motifs)
Diseases named in the same sentence as RECK in open-access papers (continued):
Sharing a sentence is not in itself a finding about the gene and the disease.
colorectal cancer (16 papers, 2006 to 2024). A primary or metastatic malignant neoplasm that affects the colon or rectum. "Of note, miRNA-342 has been shown to be downregulated in colorectal cancer tissues and cell lines, and restoring its expression while increasing RECK expression markedly reduced the proliferation and migration of a colorectal cancer cell line." (PMID 39451191, 2024). "On the contrary, miR-375-3p has also been identified as an oncogene in colorectal cancer because of its ability to promote invasion and migration by targeting RECK." (PMID 35205628, 2022). "Another study determined that miR-200b/c targeted RECK and subsequently upregulated Skp2 expression and inhibited p27 levels in colorectal cancer cells, resulting in enhanced cell proliferation." (PMID 33621206, 2021). "A positive correlation has been observed between the abundance of RECK expression in tumor samples and a more favorable prognosis for patients with several types of tumors, such as gastric, lung, pancreatic and colorectal cancer." (PMID 26431549, 2015). "The potential prognostic power of RECK has already been reported for other tumors, such as pancreatic, liver, lung and colorectal cancers, where RECK expression is inversely correlated with MMP expression during tumor progression." (PMID 26449734, 2015). "The present result corroborates previous observation of positive correlation between the abundance of the canonical RECK expression and better prognosis of patients with gastric, lung, pancreatic and colorectal cancers." (PMID 26431549, 2015). "An increasing amount of evidence has now indicated that the altered expression of RECK is involved in numerous solid tumors, including lung cancer, human breast carcinoma, pancreatic cancer, non-small cell lung cancer and colorectal cancer." (PMID 24765174, 2014). "RECK was found with cytoplasmic granular staining as shown for prostate carcinoma, urothelial bladder carcinoma and colorectal carcinoma, although membranous staining described for the other tumor entities was not prominent." (PMID 24131772, 2013). "Low RECK expression colorectal cancer and esophageal cancer patients exhibited more lymph node metastasis." (PMID 22428065, 2012). "When the data were combined, a combination of MMP-7 and SLC5A8 (and, to a lesser extent, RECK) provided the greatest separation between healthy colon tissue and colorectal cancer (tissue or cell lines)." (PMID 19689820, 2009). "Likewise, a study conducted in a cohort of 283 colorectal cancer patients implied that reduced RECK expression was an independent prognostic biomarker of poor survival." (PMID 27530410, 2016). "RECK, initially identified as a transformation suppressor gene, is normally expressed in adult human tissues and is downregulated in numerous solid tumors, including pancreatic cancer, non-small cell lung cancer and colorectal cancer." (PMID 24765174, 2014).
prostate carcinoma (16 papers, 2005 to 2024). A carcinoma that arises from epithelial cells of the prostate gland. "This study aimed to evaluate the application of MMP-9 and its regulators (TIMP-1, RECK, and miR-338-3p) as diagnostic and prognostic indicators of prostate cancer." (PMID 35097136, 2021). "We have previously shown that FOXB2 controls Wnt pathway activity in prostate cancer cells via WNT7/RECK, suggesting that these and potentially other FOX family members are functionally redundant in the context of Wnt/β-catenin signaling." (PMID 37011861, 2023). "It should be noted that RECK shows its tumor suppressor function by reducing the invasion of prostate cancer by inhibiting MMP-2." (PMID 37438760, 2023). "RECK expression has been reported to be down regulated in several cancers including prostate cancer." (PMID 23383207, 2013). "In our study, we observed that miR-182 inhibitor decreased active-MMP-2 expression in prostate cancer cell lines as well as up-regulation of RECK protein." (PMID 23383207, 2013). "To determine if RECK is a target of miR-21 in prostate cancer we performed an in vitro assay with PCa cell line DU-145 transfected with pre-miR-21 and anti-miR-21." (PMID 22642976, 2012). "In this study, we will investigate if RECK is a target of miR-21 in prostate cancer cell line DU-145 in in vitro assays." (PMID 22642976, 2012). "In this first study we identify a possible role of miR-21 in the behavior of prostate cancer promoting a decay in the levels of RECK mRNA allowing the overexpression of MMP9." (PMID 22642976, 2012). "Investigations on whether RECK is a target of miR-21 in the DU-145 prostate cancer cell line have revealed that miR-21 directly inhibits RECK and plays a significant role in the progression of prostate cancer by controlling RECK." (PMID 39114567, 2024). "MiR-15b-5p promotes tumorigenesis of prostate cancer by modulating the expression of RECK." (PMID 33526036, 2021). "As shown, RECK inhibited cell migration and invasion in prostate cancer cells." (PMID 23383207, 2013). "Additionally we investigated RECK function by over expressing it in prostate cancer cell lines (PC-3 and DU 145)." (PMID 23383207, 2013). "However our results show that miR-182-5p directly regulates RECK expression in prostate cancer cell lines." (PMID 23383207, 2013). "We therefore believe that miR-21 may be playing a role in a subset of prostate cancers through regulation of RECK expression levels." (PMID 22642976, 2012). "Inhibition of miR-182-5p by an inhibitor of this microRNA also resulted in the suppression of invasion and migration in prostate cancer cells via upregulation of FOXF2, RECK, and MTSS1." (PMID 37438760, 2023). "Another study reported that three genes, FOXF2, RECK, and MTSS1, which act as tumor suppressors and are involved in inhibiting the development of prostate cancer cells by reducing invasion and migration, were targeted by miR-182-5p." (PMID 37438760, 2023). "We found that most patients with prostate cancer overexpressed MMP-9; on the other hand, most of them underexpressed TIMP-1, RECK, and miR-338-3p." (PMID 35097136, 2021). "Approximately 58% of the patients with prostate cancer presented MMP9 upregulation, while 73%, 65%, and 69% downregulated IMP-1, RECK, and miR-338-3p, respectively." (PMID 35097136, 2021). "In-vitro studies showed that the knock-down of miR-182-5p in prostate cancer cell can promote cell proliferation, migration and invasion by regulating the potential targets of FOXF2, RECK and MTSS1." (PMID 32102688, 2020). "Cell viability, invasion and migration were significantly inhibited in RECK and MTSS1 transfected prostate cancer cells." (PMID 23383207, 2013). "Since we focused on three target genes (RECK, MTSS1 and FOXF2) and investigated only 52 clinical samples, additional studies will be needed to elucidate the role of miR-182-5p in prostate cancer and its use in clinical applications." (PMID 23383207, 2013).
prostate carcinoma (continued). "To examine the function of RECK and MTSS1, we overexpressed RECK and MTSS1 in prostate cancer cells which were confirmed by measuring mRNA and protein expression levels." (PMID 23383207, 2013). "Additionally the levels of FOXF2, RECK and MTSS1 were significantly higher in xenograft tissues from low miR-182-5p expressing prostate cancer cells." (PMID 23383207, 2013). "Also knock down of miR-182-5p in order to increase expression of tumor suppressor genes FOXF2, RECK and MTSS1 may be of therapeutic benefit in prostate cancer treatment." (PMID 23383207, 2013). "Additionally knocking down of miR-182-5p with inhibitor may be of therapeutic benefit for enhancing expression of tumor suppressor genes FOXF2, RECK and MTSS1 in prostate cancer cells." (PMID 23383207, 2013).
oral cancer (11 papers, 2008 to 2024). "Similar to our study, our previous studies showed that genetic polymorphisms of an oncogene (e.g., CA-9) or tumor suppressor gene alone (e.g., RECK) were unable to predict the risk of oral cancer." (PMID 25806809, 2015). "Moreover, the keratinization process is associated with poor prognosis of patients with oral cancer, and keratinization-associated microRNAs mediate deregulation of RECK, which may contribute to the aggressiveness of tumors." (PMID 38612895, 2024). "Their findings show that EGCG therapy of oral cancer cells partly reverses the hypermethylation status of the RECK gene and greatly increases RECK mRNA expression." (PMID 35327559, 2022). "The expression levels of RECK mRNA in 4 human oral cancer cell lines and HeLa were examined by RT–PCR." (PMID 18665171, 2008). "The results showed that treatment of oral cancer cells with EGCG partially reversed the hypermethylation status of the RECK gene and significantly enhanced the expression level of RECK mRNA." (PMID 18665171, 2008). "Our results showed that treatment of oral cancer cells with EGCG partially reversed the hypermethylation status of the RECK gene and significantly enhanced the expression level of RECK mRNA." (PMID 18665171, 2008). "In betel quid-chewing oral cancer patients, those who have the RECK rs10814325 polymorphism have a higher risk of neck lymph node metastasis than wild type carriers." (PMID 22428065, 2012). "Taken together, these findings provide compelling evidence that targeting RECK, a keystone protein that regulates mediators of invasion and angiogenesis with phytochemicals such as nimbolide may be a robust therapeutic approach to prevent oral cancer progression." (PMID 28515436, 2017). "Further, we provide evidence to demonstrate that nimbolide activates RECK by inhibiting miR-21 and HIF-1α under hypoxic conditions in a cellular context using the oral cancer cell lines SCC131, SCC4 and the endothelial cell line EAhy926." (PMID 28515436, 2017).
bladder cancer (10 papers, 2012 to 2024). "For instance, the MMP repressor RECK (in our analysis hypothetically down-regulated in cancer by miR-429), which decrease was found associated with more invasive forms of bladder cancer." (PMID 23717626, 2013). "While in bladder cancer miR-182-5p can regulate the expression levels of Smad4 and RECK, and high-expression of miR-182-5p can significantly shorten the overall survival of bladder cancer patients." (PMID 32102688, 2020). "High expression of Ras protein and RbAp46 protein and low expression of RECK protein were detected in bladder cancer specimens." (PMID 25885317, 2015). "Using bladder cancer T24 cells, our data consistently showed that RbAp46 protein expression was decreased and RECK protein expression was increased when Ras was suppressed by Ras shRNA lentivirus." (PMID 25885317, 2015). "The relationship among Ras, RbAp46 and RECK expression was also detected in 75% (3/4) of the bladder cancer specimens analyzed." (PMID 25885317, 2015). "Our findings also showed clinical evidence of a relationship among Ras, RbAp46 and RECK in bladder cancer." (PMID 25885317, 2015). "In summary, we have demonstrated a correlation among Ras-RbAp46-RECK in bladder cancer specimens, indicating the importance of Ras, RbAp46 and RECK in bladder tumorigenesis." (PMID 25885317, 2015). "The expression levels of Ras, RbAp46 and RECK were also determined in human bladder cancer specimens." (PMID 25885317, 2015). "In bladder cancer, miR-182 promotes the cell proliferation, migration and invasion by suppressing Smad4 and RECK." (PMID 24884732, 2014). "RECK is crucial repressor of matrix metalloproteinases (MMPs) and previous studies have shown that RECK expression is significantly lower in bladder cancer tissues compared to normal urothelial tissues." (PMID 23226455, 2012). "As shown, RECK inhibited cell proliferation, migration and invasion abilities in bladder cancer cells and the number of apoptotic cells was increased by RECK transfection." (PMID 23226455, 2012). "Taken together, this study shows that miR-182-5p exerts its oncogenic effects in bladder cancer cells by down-regulating RECK and Smad4." (PMID 23226455, 2012). "We also investigated the function of RECK by over expressing it in a bladder cancer cell line (T24)." (PMID 23226455, 2012). "Cell viability, invasion and migration were significantly inhibited in RECK and Smad4 transfected T24 bladder cancer cells." (PMID 23226455, 2012). "In conclusion, our data suggests that miR-182-5p plays an important role as an oncogene by knocking down RECK and Smad4, resulting in activation of the Wnt-beta-catenin signaling pathway in bladder cancer." (PMID 23226455, 2012). "Finally, RbAp46 expression was found to be associated with mutant Ras expression and was inversely correlated with the expression of RECK in bladder cancer tissues." (PMID 25885317, 2015). "Finally, we over-expressed these target genes (Smad4 and RECK) in bladder cancer cells to examine the mechanism of miR-182-5p function." (PMID 23226455, 2012). "This is the first report to also document that miR-182-5p expression is significantly increased in bladder cancer tissues where it functions as an oncogene by inhibiting RECK and Smad4 expression and may be potentially useful as a prognostic biomarker." (PMID 23226455, 2012). "We further investigated these genes using the Oncomine database, and the results also indicated lower expression of PDE5A, RECK, ZEB2, and CYBRD1 in bladder cancer tissue than in normal bladder mucosa." (PMID 33987019, 2021). "In this study, we reveal that Ras up-regulates RbAp46 expression in human breast and bladder cancer cells as well as in mouse fibroblast 7–4 cells, and the binding of RbAp46 with HDAC and Sp1 represses RECK promoter activation via the Sp1 site." (PMID 25885317, 2015).
bladder cancer (continued). "RECK is a crucial MMP-2 repressor and RECK expression was previously reported to be down regulated in bladder cancer tissues compared to normal urothelium." (PMID 23226455, 2012). "Further analysis of gene expression from the GEO dataset indicated lower expression of PDE5A, RECK, ZEB2, and CYBRD1 in bladder cancer tissue than in normal bladder mucosa, which indicated that PDE5A, RECK, ZEB2, and CYBRD1 may act as tumor suppressors in UTUC." (PMID 33987019, 2021).
cervical carcinoma (10 papers, 2012 to 2024). A carcinoma arising from either the exocervical squamous epithelium or the endocervical glandular epithelium. "In cervical carcinoma, RECK expression is associated with the recruitment of tumor-infiltrating lymphocytes and the expression of immune checkpoint molecules, including programmed cell death ligand 1 (PD-L1)." (PMID 38612895, 2024). "Lower RECK mRNA levels are associated with cervical lesion progression and poor response to chemotherapy in cervical cancer patients." (PMID 38612895, 2024). "Similar to KEGG pathway enrichment data from our mouse models, we showed here that the cell adhesion process was associated with RECK mRNA expression in cervical cancer (orange arrow)." (PMID 34066355, 2021). "Our data are consistent with other groups’ reports that changes in RECK gene expression could represent a risk factor in cervical cancer development." (PMID 38612895, 2024). "Finally, we found that lower RECK mRNA levels were associated with cervical lesions progression and worse response to chemotherapy in cervical cancer patients." (PMID 34066355, 2021). "Our findings indicate that miR-21 post-transcriptionally down-regulates the expression of RECK to promote cell proliferation and cell migration inhibition in cervical cancer cell survival." (PMID 38612895, 2024). "We report that overexpression of miR-21 post-transcriptionally downregulates the expression of RECK and inhibits cell proliferation and migration of human cervical cancer cells transformed with HPV16 (CaSki and SiHa cells)." (PMID 38612895, 2024). "This study shows that silencing of miR-21 induces the reestablishment of RECK gene and protein expression in cervical cancer cells." (PMID 38612895, 2024). "In particular, the molecular mechanism through which the RECK gene is regulated by miR-21 in cervical cancer is poorly studied." (PMID 38612895, 2024). "In the present study, we analyze the role of miR-21 in RECK gene regulation in cervical cancer cells." (PMID 38612895, 2024). "RECK is widely expressed in normal human tissues and is downregulated in a wide variety of tumor tissues, including cervical cancer, and its under-expression often correlates with poorer prognoses." (PMID 38612895, 2024). "The major novel contribution of our data is to demonstrate that RECK gene expression is regulated by miR-21 in HPV-positive cervical cancer cells, and this regulation occurs mainly through MRE21-1, MRE21-2, and MRE21-3 within the RECK 3′-UTR regulatory region." (PMID 38612895, 2024). "We found that in cervical cancer cells, there was an inverse correlation between miR-21 expression and RECK mRNA and protein expression." (PMID 38612895, 2024). "We observed that RECK gene expression and RECK cell protein expression were both reestablished in HPV16-transformed cervical cancer cells (CaSki and SiHa cells) when miR-21 expression was silenced with specific siRNAs to miR-21." (PMID 38612895, 2024). "Silencing miR-21 induces the reestablishment of RECK gene and protein expression, leading to biological effects which include inhibition of cervical cancer cell migration and proliferation." (PMID 38612895, 2024). "This evidence strongly supports the notion of a regulatory genetic network between miR-21 and RECK in HPV-transformed cervical cancer cells." (PMID 38612895, 2024). "This mechanistic insight highlights miR-21's role in promoting cervical cancer progression by downregulating RECK." (PMID 39512697, 2024). "Previous results from our laboratory indicate that RECK down regulation is important in cervical cancer natural history." (PMID 34066355, 2021). "RECK+ tumors exhibited an enrichment of cell adhesion processes both in the mouse model and cervical cancer clinical samples." (PMID 34066355, 2021). "First, we injected RECK+ cervical cancer derived cells in nude mice and interrupted the experiment when tumors from the control group reached approximately 500 mm3." (PMID 34066355, 2021).